OLFM4 (olfactomedin 4)
Diseases named in the same sentence as OLFM4 in open-access papers (continued):
Sharing a sentence is not in itself a finding about the gene and the disease.
septic shock (6 papers, 2021 to 2025). Shock caused by infection; frequently caused by gram negative bacteria, although some cases have been caused by other bacteria, viruses, fungi, and protozoa; characterized by fever, chills, tachycardia, tachypnea, and hypotension. "Expression levels of NDUFAF1 in two central nodes involved in epidermal growth factor (EGF) and Olfactomedin 4 (OLFM4) have been associated with acute kidney injury and septic shock." (PMID 38783263, 2024). "In pediatric patients with septic shock, increased OLFM4 mRNA transcription, plasma protein levels, and a greater percentage of OLFM4 positive neutrophils are independently associated with multiorgan failure and death." (PMID 36117416, 2022). "Moreover, OLFM4 (OR = 1.006, 95% CI 1.003–1.010, P < 0.001), miR-122-5p (OR = 1.485, 95% CI 1.021–2.158, P = 0.038), and miR-125b-5p (OR = 1.729, 95% CI 1.101–2.715, P = 0.017) emerged as independent predictors of septic shock." (PMID 39901167, 2025). "Among children with septic shock, elevated MMP8 and OLFM4 blood gene expression levels, which are markers of neutrophil activation, are associated with higher rates of mortality and organ failure." (PMID 33006196, 2021).
colitis (5 papers, 2021 to 2023). Inflammation of the colon. "Compared with wild-type littermates, olfactomedin-4 knockout mice were more susceptible to dextran sulfate sodium-induced colitis and produced higher levels of proinflammatory cytokines and chemokines." (PMID 37151883, 2023). "Interestingly, compared with their WT littermates, Olfm4-/- mice showed increased susceptibility to DSS-induced colitis." (PMID 37151883, 2023). "To further explore the in vivo function of Olfm4 in colitis, we generated Olfm4-/- mice and established a mouse model of acute colitis by adding 35 g/L DSS to the drinking water." (PMID 37151883, 2023). "AAV-mediated inhibition of Mmp9 significantly ameliorated DSS-induced clinical and pathological manifestations of colitis in the Olfm4-/- mice." (PMID 37151883, 2023). "Histological analyses confirmed that re-expression of Olfm4 significantly ameliorated colitis in the DSS-treated Olfm4-/- mice." (PMID 37151883, 2023). "To explore the function of OLFM4 in colitis, we assessed the effects of OLFM4 knockdown or overexpression on LPS-stimulated inflammation in HCT116 cells." (PMID 37151883, 2023). "We performed next-generation RNA sequencing to explore the regulatory mechanisms of OLFM4 in colitis." (PMID 37151883, 2023). "In our study, we believe that Olfm4 is upregulated in the inflammatory state to protect against the development of colitis." (PMID 37151883, 2023). "We also found that Olfm4 deletion leads to an enhanced immune response and inflammation in the progression of colitis, characterized by enhanced expression of complement Il-1β, Il-6, and Mcp-1 and activation of the NF-κB pathway." (PMID 37151883, 2023). "We found that body weight, colon length, and H&E staining all indicated more severe and extensive colitis in the Olfm4-/- mice than in the WT littermates." (PMID 37151883, 2023). "We observed a significant increase in Olfm4 expression in active UC patients and in cellular and mouse models of colitis." (PMID 37151883, 2023). "These candidate biomarkers, MST1L, OLFM4, and DPP10, were predicted to be strongly associated with immune cell infiltration of colitis, especially γδ T cells, neutrophils, and macrophages M1." (PMID 34939750, 2022). "Our results showed that the mRNA levels of ISC maker genes, including Lgr5, Olfm4 and Ascl2, were significantly increased in the colon of colitis mice after L-fucose treatment." (PMID 36432480, 2022). "To explore whether MMP9 mediated the regulatory effects of OLFM4 on colitis in mice, we transfected Olfm4-/- mice and WT littermates with recombinant adeno-associated virus-shMMP9 (AAV-shMMP9) or control vectors (AAV-shNC) through tail vein injection." (PMID 37151883, 2023). "This study focused on the role and regulatory mechanisms of OLFM4 in colitis." (PMID 37151883, 2023). "To further confirm whether NOTCH1 is essential for OLFM4 to regulate colitis, we inhibited the Notch signaling pathway by DAPT47." (PMID 37151883, 2023).
colitis (continued). "We also observed that the expression of MMP9 was dramatically upregulated at both the mRNA and protein levels in the cellular and mouse models of colitis, and knockout of Olfm4 further upregulated the expression of MMP9 in LPS-stimulated cells and in the colon of DSS-treated mice." (PMID 37151883, 2023). "Likewise, real-time quantitative PCR showed that the mRNA expression of the ISC marker genes Lgr5, Olfm4 and Ascl2 was increased in the L-fucose-treated colitis mice." (PMID 36432480, 2022). "Moreover, Olfm4 deletion exacerbated inflammation and mucosal damage in a mouse model of colitis, further supporting its role in immune restraint." (PMID 34884869, 2021). "To further confirm the differential expression of these candidate genes between ulcerative colitis and normal groups, we determined the mRNA expression of SGK1, CEP55, ACSL1, OLFM4, MGP, and DPP10 in colon tissues of DSS‐induced colitis mice." (PMID 34939750, 2022). "We also examined SGK1, CEP55, ACSL1, OLFM4, DPP10, and MGP expression in the colon tissues of dextran sodium sulfate‐induced colitis mice." (PMID 34939750, 2022). "In addition, we also examined the expression of SGK1, CEP55, ACSL1, OLFM4, DPP10, and MGP in the colon tissues of DSS‐induced colitis mice." (PMID 34939750, 2022). "In addition, we also examined the expression of SGK1, CEP55, ACSL1, OLFM4, DPP10, and MGP in the colon tissues of dextran sulfate sodium‐induced colitis mice." (PMID 34939750, 2022).
inflammatory bowel disease (5 papers, 2015 to 2023). A spectrum of small and large bowel inflammatory diseases of unknown etiology. "Our finding broadly supports other studies in this area linking OLFM4 over-expression with colorectal disease: van der Flier, Shinozaki, and Huang showed that higher protein levels of OLFM4 are associated with inflammatory bowel disease, adenomatous precursors, and CRC." (PMID 36691026, 2023). "OLFM4 expression is significantly upregulated in the intestinal epithelium in inflammatory bowel disease." (PMID 36831547, 2023). "The glycoprotein OLFM4 is upregulated in inflammatory bowel diseases and Helicobacter pylori infected patients." (PMID 26302420, 2015). "It is centrally discussed in pathogenesis of inflammatory bowel diseases (IBD), in which OLFM4 mRNA and protein expression levels are significantly increased in the intestinal epithelium." (PMID 35410162, 2022).
lung carcinoma (5 papers, 2015 to 2023). "Involvement of highly significant DEGs including SLCO1A2, OLFM4, RTKN2, CYP1A1, and MUC5AC plays a key role in rheumatoid arthritis development.Highly significant DEGs including OLFM4, RTKN2, CYP1A1, MUC5AC, CYP2A6, PCK1, and PITX1 have been reported to encourage the development of lung cancer." (PMID 38137330, 2023).
ulcerative colitis (5 papers, 2010 to 2025). An inflammatory bowel disease involving the mucosal surface of the large intestine and rectum. "In this study, we aimed to explore the role and underlying regulatory mechanism of OLFM4 in ulcerative colitis." (PMID 37151883, 2023). "Selective over-expression of OLFM4 has been reported in inflamed colonic crypt epithelium in ulcerative colitis patients." (PMID 20941359, 2010). "First, OLFM4 may regulate ulcerative colitis through a more complex mechanism than previously discovered." (PMID 37151883, 2023). "In addition, OLFM4 was only expressed in the ulcerative colitis samples and DPP10 was only found in the normal samples." (PMID 34939750, 2022). "Finally, one of the genes involved in the inflammatory process (OLFM4) is already reported to be up-regulated in PBMCs together with inflamed colonic mucosa in active ulcerative colitis." (PMID 29971234, 2018). "Our findings indicated that DPP10, MST1L, DPP10‐AS1, CEP55, ACSL1, MGP, OLFM4, and SGK1 may act as diagnostic biomarkers for ulcerative colitis and that differential immune infiltration cells may help to illustrate the progression of ulcerative colitis." (PMID 34939750, 2022). "Compared with the normal group, the expression of SGK1, CEP55, ACSL1, OLFM4, and MGP was markedly increased in the DSS‐induced ulcerative colitis group." (PMID 34939750, 2022). "To further validate these biomarkers' expression in ulcerative colitis, we determined mRNA levels of SGK1, CEP55, ACSL1, OLFM4, and DPP10 in lipopolysaccharides (LPS)‐stimulated Raw264.7 cells by quantitative reverse transcription‐polymerase chain reaction." (PMID 34939750, 2022). "To further validate the expression of these candidate biomarkers in ulcerative colitis, we determined mRNA levels of SGK1, CEP55, ACSL1, OLFM4, and DPP10 in LPS‐stimulated Raw264.7 cells by qPCR in in vitro bioassays." (PMID 34939750, 2022). "Of these candidate biomarkers, MST1L, OLFM4, and DPP10 were then validated in the GSE48958 dataset and were predicted to be strongly correlated with infiltrating immune cells of ulcerative colitis." (PMID 34939750, 2022). "AUC was higher than 0.8, indicating that these genes MST1L, OLFM4, and DPP10 are indicators of ulcerative colitis." (PMID 34939750, 2022). "Furthermore, to examine the model's accuracy in distinguishing between the healthy and ulcerative colitis groups, we further determine the area under the curve (AUC) of MST1L, OLFM4, and DPP10 in GSE48958 and the combined data from GSE36807 and GSE65114." (PMID 34939750, 2022). "Correlation between MST1L, OLFM4, and DPP10 in ulcerative colitis and immune infiltration cells." (PMID 34939750, 2022). "Hence, these candidate biomarkers, MST1L, OLFM4, and DPP10, may be involved in the development of ulcerative colitis." (PMID 34939750, 2022).
acute kidney injury (4 papers, 2021 to 2025). Sudden and sustained deterioration of the kidney function characterized by decreased glomerular filtration rate, increased serum creatinine or oliguria. "Similar results were found among patients with Acute Kidney Injury (AKI) where the overexpression of genes such as MMP8, IL1R2, and OLFM4 was associated with increased severity and organ failure." (PMID 33692779, 2021). "A study indicated a correlation between septic shock and acute kidney injury (AKI), revealing that the genes PTX3, VMP1, OLFM4, SLPI, TIMP1, LCN2, and S100A9 are strongly correlated with novel biomarkers implicated in the onset and progression of sepsis‐associated acute kidney injury (SSAKI)." (PMID 41394771, 2025). "Sepsis may also induce acute kidney injury (AKI), and studies showed that VMP1, SLPI, PTX3, TIMP1, OLFM4, LCN2, and S100A9 genes were markedly correlated with the development and progression of septic-shock-associated AKI." (PMID 36299685, 2022).
Barrett esophagus (4 papers, 2018 to 2024). Esophageal lesion lined with columnar metaplastic epithelium which is flat or villiform. "OLFM4 was found to be closely linked to nodal metastases in esophageal adenocarcinoma." (PMID 34912753, 2021). "OLFM4 positive cells are also found in gastric intestinal metaplasia and Barrett’s esophagus (BE), where it is confined to the base of metaplastic glands, in a similar way as in colon crypts, with gradually increased expression during dysplastic progression." (PMID 31283789, 2019). "We find that cell populations in Barrett’s oesophagus, marked by LEFTY1 and OLFM4, exhibit a profound transcriptional overlap with oesophageal submucosal gland cells, but not with gastric or duodenal cells." (PMID 30323168, 2018). "In normal esophageal tissue (without presence of Barrett’s esophagus), OLFM4 expression was absent." (PMID 31283789, 2019). "Non-dysplastic Barrett’s esophagus (NDBE) showed a similar staining pattern as normal human colon, with cytoplasmic OLFM4 expression in the crypt basis." (PMID 31283789, 2019).
depression (4 papers, 2023 to 2025). "Recent genome-wide association studies on major depressive disorder (MDD) have implicated LRFN5 and OLFM4, but their expressions and roles in MDD are still completely unclear." (PMID 37280213, 2023). "Interestingly, we also found correlations between the levels of these aberrant clinical biochemical indices and the levels of LRFN5 or OLFM4, which further supported their involvement in depression." (PMID 37280213, 2023). "However, till now, very little is known about the expression and function of LRFN5 and OLFM4 in patients with depression." (PMID 37280213, 2023). "Given that the levels of LRFN5 and OLFM4 were elevated in the serum of patients with MDD, and lower in DT-MDD patients than in DN-MDD patients, they might be used as additional state or trait biomarkers for depression." (PMID 37280213, 2023).
head and neck squamous cell carcinoma (4 papers, 2014 to 2025). A squamous cell carcinoma that arises from any of the following anatomic sites: lip and oral cavity, nasal cavity, paranasal sinuses, pharynx, larynx, and salivary glands. "OLFM4, olfactomedin-4, is reported to be significantly increased in head and neck squamous cell carcinoma (75% tested), suggesting a potential biomarker in this type of cancer." (PMID 38067138, 2023). "Overexpression of OLFM4 was found in 75% of head and neck squamous cell carcinomas (HNSCC) validated by immunohistochemistry (IHC), and OLFM4 level is markedly increased in the supernatants of HNSCC cells." (PMID 24495253, 2014).
lymph node metastasis (4 papers, 2014 to 2021). "The clinicopathological factors and OLFM4 expression were co-analyzed to predict lymph node metastasis in EGC." (PMID 27294866, 2016). "We found that OLFM4 was upregulated in EGC tumor sections, and relatively low expression of OLFM4 was observed in patients with lymph node metastasis." (PMID 27294866, 2016). "OLFM4 expression as well as tumor size and differentiation were identified as independent factors, which could be co-analyzed to generate a better model for predicting lymph node metastasis in EGC patients." (PMID 27294866, 2016). "Our study implies that OLFM4 expression is a potential predictor of lymph node metastasis in EGC, and combing OLFM4 with tumor size and differentiation could better stratify EGC patients with different risks of lymph node metastasis." (PMID 27294866, 2016).
melanoma (4 papers, 2014 to 2025). A malignant, usually aggressive tumor composed of atypical, neoplastic melanocytes. "In mouse melanoma cell lines, OLFM4 has been shown to suppress cancer growth and metastatic potential by downregulating integrin and MMP genes, suggesting a tumor-suppressive function in certain cancers." (PMID 39861713, 2025). "In the Melanoma B16F10 model, OLFM4 has also been reported to play a role in tumor progression and immune evasion mechanisms." (PMID 39861713, 2025). "It was found that OLFM4 significantly suppressed the tumourigenicity of mouse melanoma cell B16F10, but had no positive effect on cell viability or cell cycle progression." (PMID 24495253, 2014).
acute respiratory distress syndrome (3 papers, 2020 to 2022). Progressive and life-threatening pulmonary distress in the absence of an underlying pulmonary condition, usually following major trauma or surgery. "Increased transcription of OLFM4 from whole blood samples is associated with increased disease severity in adults with acute respiratory distress syndrome and children with respiratory syncytial virus." (PMID 32470072, 2020). "OLFM4 gene expression in the whole blood was upregulated in septic patients with acute respiratory distress syndrome." (PMID 36035204, 2022).
colon adenocarcinoma (3 papers, 2019 to 2023). "Previous studies have described the proinflammatory effect of OLFM4 in colon adenocarcinoma, but this study focused on the occurrence of adenocarcinoma, which is very different from ulcerative inflammation." (PMID 37151883, 2023). "Both Wnt and NF-κB signaling pathways are boosted in colon adenocarcinoma tissues of Apc Olfm4 double-mutant mice." (PMID 30808715, 2019).
lung adenocarcinoma (3 papers, 2019 to 2025). A carcinoma that arises from the lung and is characterized by the presence of malignant glandular epithelial cells. "MiR-590 (miR-590-3p) promotes A549 lung adenocarcinoma cell migration and invasion by targeting olfactomedin 4 (OLFM4), inhibiting tumor cell adhesion." (PMID 30813457, 2019). "Moreover, investigators found that miR-590-3p inhibited the expression of OLFM4 protein by binding to the 3’UTR site of OLFM4, which is its downstream target gene, thus promoting invasion and metastasis of lung adenocarcinoma." (PMID 34306018, 2021).
psoriasis (3 papers, 2022 to 2023). An autoimmune condition characterized by red, well-delineated plaques with silvery scales that are usually on the extensor surfaces and scalp. "We found that the expression of OLFM4 was increased in human skin graft-treated burn wounds, in lesions of a chronic inflammatory dermatosis—psoriasis—and during skin wound healing in mice." (PMID 35218417, 2022). "An interesting aspect worth of further studies is also the potential involvement of OLFM4 in the pathogenesis of psoriasis and prevention of fibrosis." (PMID 35218417, 2022). "Moreover, a significant increase in OLFM4 expression was detected in the skin of lesional psoriasis, a chronic inflammatory disease characterized by keratinocyte hyperproliferation." (PMID 35218417, 2022). "As our in vitro and in vivo experiments demonstrated that OLFM4 promoted keratinocyte proliferation and wound healing it is possible that this protein may participate in the pathogenesis of psoriasis by contributing to the maintenance of keratinocyte hyperproliferation in psoriatic skin lesions." (PMID 35218417, 2022). "Interestingly, the increase in OLFM4 level was detected in hyperproliferative lesions of the psoriasis patients suggesting that stimulation of keratinocyte proliferation may underlie the stimulatory effects of OLFM4 on wound healing." (PMID 36506087, 2022). "However, the frequency of CD177+ and OLFM4+ neutrophils is not elevated in psoriasis patients compared to healthy controls, and the actual degree of heterogeneity of neutrophils in psoriasis and the underlying mechanisms remain unclear." (PMID 37736772, 2023).